CAPN12 (calpain 12)
Description:
Calcium-regulated non-lysosomal thiol-protease.
Tractability: No criterion of Open Targets' tractability assessment is met for any kind of drug.
Gene: Protein-coding gene on chromosome 19 (38,730,187 to 38,769,904, reverse strand). Ensembl gene ENSG00000182472.
Subcellular location (Human Protein Atlas): Focal adhesion sites; Nucleoplasm
Pathways (Reactome):
Extracellular matrix organization: Degradation of the extracellular matrix
Gene Ontology:
Molecular function: calcium-dependent cysteine-type endopeptidase activity; calcium ion binding
Biological process: proteolysis
Cellular component: cytoplasm
Genetic constraint (gnomAD): Loss-of-function variants: 107 observed, 89.89 expected, observed/expected ratio (o/e) 1.19, 90% interval 1.02 to 1.4. The synonymous counts are far from expectation, so gnomAD's model fits this gene poorly and the ratio says little. Missense variants: 1,128 observed, 961.05 expected, observed/expected ratio (o/e) 1.17, 90% interval 1.12 to 1.23. Synonymous variants: 501 observed, 404.55 expected, observed/expected ratio (o/e) 1.24, 90% interval 1.15 to 1.33.
Homologues: Orthologues: macaque CAPN12 (96% identical), chimpanzee CAPN12 (91% identical), dog CAPN12 (89% identical), pig CAPN12 (88% identical), mouse Capn12 (86% identical), rat Capn12 (86% identical), guinea pig CAPN12 (72% identical), rabbit CAPN12 (72% identical), tropical clawed frog XB5844015 (44% identical), Drosophila melanogaster CalpB (36% identical), Caenorhabditis elegans clp-1 (28% identical), Caenorhabditis elegans clp-7 (28% identical), and 7 more. Paralogues in human: CAPN1 (43% identical), CAPN2 (42% identical), CAPN8 (42% identical), CAPN11 (40% identical), CAPN3 (40% identical), CAPN9 (38% identical), CAPN14 (33% identical), CAPN13 (28% identical), CAPN5 (26% identical), CAPN6 (25% identical), CAPN10 (24% identical), CAPN15 (20% identical), and 8 more.
Diseases named in the same sentence as CAPN12 in open-access papers:
CAPN12 is named in the same sentence as 15 diseases in open-access papers, as found by Europe PMC text mining. Sharing a sentence is not in itself a finding about the gene and the disease. The quoted sentences say what the papers report.
atrial fibrillation (2 papers, 2019 to 2024). A disorder characterized by an electrocardiographic finding of a supraventricular arrhythmia characterized by the replacement of consistent P waves by rapid oscillations or fibrillatory waves that vary in size, shape and timing and are accompanied by an irregular ventricular response. "Notably, the ACTN4/CAPN12 locus associated with TortV is also associated with coronary artery disease, heart rate, and atrial fibrillation." (PMID 31597446, 2019). "ACTN4/CAPN12 has been linked to CAD and the pathophysiology of atrial fibrillation." (PMID 38601677, 2024).
medulloblastoma (1 paper, 2023). A malignant, invasive embryonal neoplasm arising from the cerebellum.
psoriasis (1 paper, 2025). An autoimmune condition characterized by red, well-delineated plaques with silvery scales that are usually on the extensor surfaces and scalp. "BIN2 and CAPN12 are linked to an increased risk of psoriasis." (PMID 41328434, 2025). "Additional Mendelian randomization analysis pinpointed seven marker genes linked to psoriasis: BIN2, CAPN12, CXXC5, KLRC1, KLRD1, PRF1, and SLFN5." (PMID 41328434, 2025). "Although fatty acid metabolism and cGMP–PKG signaling (CAPN12) may seem peripheral to psoriasis, both map onto clinically observed immunometabolic and vascular phenotypes." (PMID 41328434, 2025). "Apart from this study, CAPN12’s involvement was not previously reported, indicating that its association with psoriasis is a relatively novel discovery." (PMID 41328434, 2025). "By integrating single-cell RNA sequencing with MR analysis, we identified seven psoriasis-related genes (BIN2, CAPN12, CXXC5, KLRC1, KLRD1, PRF1, and SLFN5) that are highly expressed in CD4+ T cells." (PMID 41328434, 2025). "The seven genes span established–emerging–novel tiers: PRF1 and KLRC1/KLRD1 are established in psoriasis immunity; SLFN5 is a recently reported systemic inflammatory marker; BIN2/CXXC5/CAPN12 lack prior links, suggesting novelty." (PMID 41328434, 2025). "Historically, CAPN12 has not been a well-known psoriasis gene." (PMID 41328434, 2025).
tumor (5 papers, 2020 to 2025). "CAPN12, on the other hand, exhibits minimal expression in immune cells, with limited evidence linking it to tumor proliferation rather than immune regulation, implying a likely non-immune-specific role." (PMID 41328434, 2025).
cancer (1 paper, 2023). A tumor composed of atypical neoplastic, often pleomorphic cells that invade other tissues. "Besides, CAPN12 and MSC correlated with the infiltration of multiple immune cells in most cancer types." (PMID 37025600, 2023).
CAPN12 also shares sentences with these, for which no sentence is quoted: bladder urothelial carcinoma (1 paper); breast carcinoma (1); coronary artery disease (1); gastric cancer (1); hearing loss (1); hepatocellular carcinoma (1); Intellectual disability (1); laryngeal carcinoma (1); lung carcinoma (1); Sézary syndrome (1).